CXCL5 (C-X-C motif chemokine ligand 5)
Diseases named in the same sentence as CXCL5 in open-access papers (continued):
Sharing a sentence is not in itself a finding about the gene and the disease.
tumor (continued). "CXCL5 is a chemokine that promotes tumor formation by triggering the migration of CXCR2+ immune cells to tumors." (PMID 36980564, 2023). "For the purposes of validation, we selected CXCL5 due to its highest-fold change and performed IHC in posttreatment tumor specimens with residual pathological disease." (PMID 36183015, 2023). "The abundances of CXCL1, CXCL2, and CXCL5 in the lungs of C57 mice with EO771 tumor were 38.0-fold, 19.6-fold, and 10.8-fold, respectively, higher than that in the lungs of BALB/c mice with 4T1 cancer." (PMID 37553342, 2023). "Among these, CXCL5 secreted by vascular endothelial cells plays a crucial role in mediating tumor cell migration to blood vessels." (PMID 37015905, 2023). "CXCL2 and CXCL5 negatively correlated with proliferation, angiogenesis, recruitment of MDSCs, and positively correlated with tumor infiltration by NK cells." (PMID 37686093, 2023). "CXCL5 is one of the main chemokines that attract MDSCs, which are important regulators of immune responses, to the tumor." (PMID 37865750, 2023). "For example, we found that the expression of CXCL5 was upregulated, and the expression of this gene was previously shown to be increased during efferocytosis of tumor cells." (PMID 38162643, 2023). "Due to the hypoxic conditions in tumor, tumor cells express more neutrophil-associated chemokines (CXCL1, CXCL2, and CXCL5) and HMGB1 to rapidly recruit neutrophils." (PMID 38023616, 2023). "The Ma1 cluster characteristically expressed SPP1, as well as high expression of marco which can promote M2 macrophage polarization, meanwhile CXCL5, which promotes tumor metastasis, was also highly expressed in this subpopulation." (PMID 37675100, 2023). "The CXCL5/CXCR5 axis has tumorigenic capacity by stimulating tumor growth and metastatic potential of PCa." (PMID 36614308, 2023). "In a mouse model of breast cancer, tumor-associated mesenchymal stromal cells released CXCL1, CXCL2 and CXCL5, leading to increased neutrophil recruitment at primary tumor sites." (PMID 37566060, 2023). "Overexpression of CXCL5 can chemo‐attract T cells and neutrophils and contribute to tumor angiogenesis." (PMID 37675835, 2023). "RET/PTC rearrangements, implicated in HT, activate pathways that induce both HT and the expression of genes like CXCL5 and CXC chemokine receptor 2 (CXCR2), linked to inflammation and tumor invasion." (PMID 38317709, 2023). "Another study showed that the recruitment of granulocytes is not primarily due to tumor cell-derived signals, but relies on the platelet-derived CXCL5/7 chemokines from platelet–tumor cell microthrombi that promote metastasis (Labelle, Begum and Hynes, 2014)." (PMID 37601099, 2023). "AB680 also promotes the myeloid‐derived suppressor cell (MDSC) chemotaxis via tumor‐derived CXCL5 in an AMP‐dependent manner." (PMID 37867243, 2023). "The CXCL5/CXCR2 axis favors migration and invasion in BC cell lines, increasing MMP-2/-9 levels through the PI3K/AKT pathway, and CXCL5 has been linked to tumor grade, muscle invasion, and poor OS." (PMID 36614308, 2023). "Data from both in vivo and in vitro models showed that the CXCR2/CXCL1 axis as well as the CXCR2/CXCL5 axis regulate neutrophil infiltration into tumor tissues, inducing epithelial–mesenchymal transition and thus aggravating malignant behavior of HCC cells." (PMID 36982370, 2023). "CXCL5 also mediates tumor progression through neutrophil recruitment and is able to directly promote the proliferation of several types of tumor cells." (PMID 36661524, 2023). "In in vivo models of tumor metastasis, injected tumor cells are immediately coated by platelets, and activated platelets subsequently release chemokines CXCL5 and CXCL7, which are chemokines attracting granulocytes." (PMID 37770941, 2023). "For instance, CXCL5, regarded as an invasive phenotype of tumor cells, can indirectly facilitate tumor growth." (PMID 37784082, 2023).
tumor (continued). "The qRT-PCR results demonstrated that four cellular senescence-related genes (CENPA, CXCL8, EZH2, and G6PD) and two chemokine-related genes (CCL26 and CXCL5) were overexpressed in tumor tissues from HCC patients compared with paraneoplastic tissues." (PMID 36670201, 2023). "LY294002, the inhibitor of PI3K, confirmed that CXCL5 derived by CAFs created an immunosuppression microenvironment by promoting PD-L1expression in tumor cells via PI3K/AKT signaling." (PMID 36275750, 2022). "Immature DCs can be recruited into the TME, attracted by tumor-secreted factors such as CCL2, CCL20/MIP3a, CCL25, CCL5, CXCL12, CXCL1, and CXCL5, while mature DCs reside in areas surrounding the tumor." (PMID 35267487, 2022). "Given that tumor-derived CXCL5 promotes tumor cell EMT and MDSC recruitment by activating CXCR2, we proposed that HSC-derived FAPα promoted tumor cell EMT and MDSC recruitment through the CXCL5/CXCR2 axis." (PMID 35951441, 2022). "The analysis of the tumor biopsy indicated the very high expression of a chemokine, C-X-C motif chemokine 5 (CXCL5)." (PMID 35877235, 2022). "Combined with chemokine receptor 2 (CXCR2), CXCL5 participated in recruiting leukocytes, proliferating tumor cells, and metastasis." (PMID 35150082, 2022). "At the same time, IL-17A induces the production of CXCL-1 and CXCL-5, leading to the recruitment of the expanded myeloid cells into the tumor where they help to establish a tumor promoting microenvironment." (PMID 36611932, 2022). "In this work, we discovered that the chemokine CXCL5 is involved in the recruitment of MDSCs, which promotes tumor metastasis." (PMID 36186898, 2022). "Our current study provides a novel link between resistin and CXCL5 under the consideration of cell–cell interaction in the tumor microenvironment." (PMID 36104403, 2022). "Accumulated evidence has shown that dysregulated CXCL5 participates in tumor metastasis and angiogenesis in human malignant tumors." (PMID 35978824, 2022). "CXCL5 also has a higher expression in ccRCC, which role in metastasis, tumor development, and angiogenesis, has led to its designation as a key biomarker and supplementary antiangiogenic treatment target." (PMID 36588797, 2022). "Even in reports where neutrophils have been shown to exert an anti-tumor effect, CXCL5 and CXCL8 were shown to positively correlate with neutrophil infiltration." (PMID 33603130, 2022). "While CXCL11 is a chemokine that mainly attracts activated T cells, allowing them to migrate to tumour sites and suppress tumours, CXCL5 and CXCL1 are chemokines with chemotactic and neutrophil-activating functions." (PMID 35740353, 2022). "A previous study has reported that the CXCL5/CXCR2 axis can facilitate tumor growth and angiogenesis and promote host cell infiltration and activation." (PMID 35936390, 2022). "Recruitment of circulating neutrophils in tumor tissues is mainly regulated by CXCL1, CXCL2, CXCL8 and CXCL5 chemokines, the complement component anaphylatoxin C5a and tumor-derived oxysterols." (PMID 35158779, 2022). "Treatment of NSCLC tumor-bearing mice with neutralizing anti-CXCL5 antibodies decreased tumor growth, tumor vascularity, and spontaneous metastases." (PMID 36612163, 2022). "Other chemokines like CXCL5 secreted by solid tumors recruited CXCR2‐expressing myeloid‐derived suppressor cells (MDSCs) to the tumor microenvironment that secrete cytokines and enzymes suppressing local T cells activation and viability." (PMID 35844304, 2022). "In this case, IRS analysis of stromal CXCL5 staining indicates that CXCL5 expression levels in tumor tissues were higher than those in normal tissues." (PMID 35853880, 2022). "CXCR2, the CXC receptor expressed by neutrophils, can bind with its ligand chemokine family (CXCL1, CXCL2, CXCL3, CXCL5, CXCL7, and CXCL8) to recruit neutrophils to the TME and participate in the mobilization of tumour-associated neutrophils." (PMID 36743929, 2022).
tumor (continued). "Taken together, our results show that FAPα induces CXCL5 secretion in HSCs to promote tumor cell EMT and MDSC recruitment through activation of CXCR2, thus facilitating vessel co-option." (PMID 35951441, 2022). "In gastric cancer stroma, neutrophils promote tumor metastasis by inducing EMT through secreting CXCL5 and IL-17a, whereas antibody-mediated IL-17a blockade suppresses EMT in cancer cells cocultured with TANs." (PMID 36091114, 2022). "PDX9228 and PDX4582 tumors exhibited high expression of CCL5 and CXCL5, respectively, two cytokines shown to mobilize MDSCs from the bone marrow and infiltrate at the tumor site." (PMID 36551639, 2022). "Deletion of IL30 dramatically downregulated BCL2, NFKB1, STAT3, IGF1 and CXCL5, whereas tumor suppressors, primarily SOCS3, were upregulated." (PMID 36224639, 2022). "C-X-C motif chemokine ligand 5 (CXCL5) is an inflammatory factor involved in multiple processes relevant to tumor formation and progression." (PMID 36497250, 2022). "In animal studies of bladder, renal cell, and CRCs, CXCL5 secreted by tumor cells binds its receptor CXCR2 and activates the downstream AKT/NF‐κB signaling pathway, thereby stimulating the proliferation and aggregation of endothelial cells." (PMID 35702353, 2022). "Neutrophils can be recruited by CXCL5, which participates in tumor progression in the tumor microenvironment." (PMID 35504887, 2022). "MDSCs in breast and renal cell carcinomas were shown to be related to tumor grade and positively correlated with CXCL5 expression." (PMID 35702353, 2022). "The protein and mRNA levels of the tumor derived from PC-WISP1v1 cells in the xenograft animal model hat indicated that the WISP1 induced CXCL5 but downregulated NDRG1 in vivo." (PMID 36232736, 2022). "IHC analysis revealed that circDHTKD1 overexpression significantly increased LN metastasis and lymphatic vessel quantities in primary tumor tissues, which were decreased by CXCL5 knockdown." (PMID 35504887, 2022). "We also summarized and discussed the perspective about the potential application of CXCL5 in tumor therapy targeting the tumor inflammatory microenvironment." (PMID 35978824, 2022). "Next, we analyzed MDSC chemotaxis-related genes, including Cxcl1, Cxcl2, Cxcl5, and Cxcl12 in tumor tissues." (PMID 34976216, 2022). "Tumor cells secrete chemokines such as CXCL5 through the migrasome to promote the infiltration of immunosuppressive cells into the interior of the tumor tissue and suppress the inflammatory response, promoting the development of tumor." (PMID 36405728, 2022). "In summary, we discovered that overexpression of HOXC10 contributed to CRC metastasis by upregulating CXCL5 expression and increased the infiltration of MDSCs into the tumor microenvironment." (PMID 36186898, 2022). "Previous studies have reported that CXCL5 is engaged in neutrophil recruitment during inflammation and drives neutrophil infiltrations into many types of tumor tissues." (PMID 36091114, 2022). "miR−432−5p also targets CXCL5 and functions as a tumor suppressor to inhibit the migration and invasion of CRC cells." (PMID 35935996, 2022). "Current research has shown that CXCL3, CXCL5, and CXCL8 were CXC chemokines strongly associated with tumor angiogenesis." (PMID 35795552, 2022). "The CXCL5/CXCR2 signaling axis can also indirectly promote tumor progression via modulating the function of various immune cells within the TME." (PMID 35702353, 2022). "CXCL5 and CXCL2 levels were high in tumor cells and tumor-associated stroma in a mouse model of PDA." (PMID 33603130, 2022). "Tumor-conditioned monocyte shown an increased migration in response to CXCL5, CXCL12, CCL3, and CCL5." (PMID 34975843, 2021). "Liberation of chemokines such as C-X-C motif chemokine 5 (CXCL5) and C-C Motif Chemokine Receptor 6 (CCR6) by primary tumor is associated with liver metastasis and worse prognosis." (PMID 33800796, 2021).
tumor (continued). "Hypoxia and interstitial acidosis are also important in the promotion of osteosarcoma bone metastasis, in part through activation of IL-8, IL-6, NF-κB1, colony-stimulating factors CSF2 and CSF3, BMP-2, CCL5, CXCL5 and CXCL1 in tumor-associated MSCs." (PMID 34831167, 2021). "Chemokines such as CXCL8, CXCR3, CXCL1, and CXCL5 regulate the tumor immune response in tumor microenvironment." (PMID 33955820, 2021). "The tumor microenvironment (TME) is regulated by chemokines and their G protein coupled receptors binds several ligands, including Cxcl5 which binds Cxcr2, to augment the pro-tumor immune response, tumor growth and metastasis." (PMID 33946495, 2021). "The quantification of Cxcr2 ligands showed that Cxcl1 and Cxcl5 RNA levels increased in the tumor of PyMT animals compared to wild−type (WT) mammary gland." (PMID 34070438, 2021). "Reexpression of DDR1 (MDA-PATC 148KD#32-ex-DDR1) rescued CXCL5 levels in the tumor and plasma as well as CD11b+Ly6G+ TAN infiltration." (PMID 34237033, 2021). "In a mouse melanoma model, CXCL5 is the primary chemokine to attract G-MDSCs to the tumor, which induced epithelial-mesenchymal transition, tumor cell migration, and metastasis." (PMID 34439836, 2021). "Serum CXCL5 levels were also significantly decreased following tumor resection in patients with PC (P=0.001)." (PMID 33458757, 2021). "Tumor cells release cytokines and chemokines such as IL-8, IL-17 and G-CSF, CXCL5 and CXCL6 that attract neutrophils from the bone marrow to tumor sites." (PMID 34261496, 2021). "CXCL5 (C-X-C motif chemokine 5) is a chemokine that mediates neutrophil trafficking, tumor cell migration, and invasion." (PMID 34298612, 2021). "S100A14 overexpressed in breast cancer cells promotes metastasis by activating the RAGE-NFκB signaling pathway resulting in the upregulation of CCL2 and CXCL5 expression in the tumor cells." (PMID 34572138, 2021). "CXCL5 is involved in recruiting immune cells to the tumor, including myeloid-derived suppressor cells, contributing to tumor immunoresistance." (PMID 34206815, 2021). "CXCL5 overexpression also regulated the expression of tumor-related genes such as ERK, p-ERK, AKT, p-AKT, DIABOL, NUMB, NDRG3, and CXCR2 at the gene level." (PMID 34833360, 2021). "In the paring analysis, the expression of CXCL5 in the tumor samples was significantly lower than that in the normal samples." (PMID 33869023, 2021). "The weights of xenograft were calculated, and the tumor weights of the CXCL5 knockdown group were lower than that of the control group (P < 0.05), whereas the body weights were not significant between the CXCL5 knockdown group and control group." (PMID 34194499, 2021). "In CRC, CXCL5 had been found to promote tumor angiogenesis, and serum CXCL5 was considered to be an indicator of prognosis in CRC patients." (PMID 33640021, 2021). "CXCL5 is often elevated in metastatic PC patients, increases with tumor apoptosis, and is thus considered as a relevant therapeutic target." (PMID 34206815, 2021). "In order to further confirm the correlation between CXCL5 expression and immune microenvironment, the proportion of tumor-infiltrating immune subsets was analyzed using CIBERSORT algorithm, and 21 kinds of immune cell profiles in HCC patients were completed." (PMID 33869023, 2021). "The differential impact of CXCL5 in cancer is suggested by the fact that it can enrich different TIICs to either accelerate or restrain TIIC involvement in tumor enlargement." (PMID 33955820, 2021). "CXCL5 is not only known to regulate neutrophil homeostasis but is also related to cancer cell migration/invasion and tumor angiogenesis." (PMID 33429364, 2021). "All tumor samples were divided into two groups based on the median expression of CXCL8 or CXCL5 and compared." (PMID 34025668, 2021). "CXCL5 from tumor cells can promote tumor growth and angiogenesis by recruiting tumor and immune cells into the TME." (PMID 34827689, 2021).
tumor (continued). "CXCL5 also induced levels of MMP2 and β-catenin that are associated with matrix remodeling during tumor progression." (PMID 34831316, 2021). "Meanwhile, the elevated expression of pro-tumor factors in neutrophils by TTCM was also down-regulated when CXCL5 neutralizing antibody was added." (PMID 32632106, 2020). "Our data are consistent with the others showing that overexpression of tumor-derived CXCL5 increases the number of intra- and peritumoral neutrophils and contributes to lymph node metastasis." (PMID 32632106, 2020). "Upon activation by tumor cells, platelets secrete CXCL5 and CXCL7 chemokines to recruit CXCR2-positive neutrophils." (PMID 33414786, 2020). "Our data showed the correlation between CXCL5 expression and suppressive immune cells, suggesting its role in shaping tumor immune microenvironment in PDAC." (PMID 32201508, 2020). "Hypoxia induced expression of CXCL1 (GRO-α), CXCL2 (MIP2α), CXCL5 (LIX) recruited anti-tumor neutrophils, which inhibited tumor growth by inducing tumor cell detachment from the basement membrane." (PMID 33262763, 2020). "The results showed that more tumor nodules were colonized in the abdomen and more metastatic tumor nodules were observed in the livers of mice in CXCL5 and 100-NCM groups than that in control and 0-NCM groups, respectively." (PMID 32632106, 2020). "In conjunction with CXCL5, high serum levels of CXCL8 in HCC have been associated with increased tumor burden, aggressiveness, and poor patient prognosis." (PMID 33718121, 2020). "The concentrations of CXCL5 in serum from GC patients, culture supernatants from tumor tissues and GC cell lines were also found to be higher than that from healthy controls, non-tumor tissues and normal gastric epithelial cell line." (PMID 32632106, 2020). "IL-17 induces the secretion of CCL2, CXCL1, CXCL5, CXCL6, and CXCL8 from several types of cells that infiltrate the tumor, and subsequently, it recruits myeloid-derived suppressor cells, including tumor-associated macrophages." (PMID 32756356, 2020). "In this study, we found CXCL5 expression was dysregulated in PDAC tumor tissues and its abundance correlated with PDAC outcome." (PMID 32201508, 2020). "CXCL5 also influences the development of an inflammatory TME by regulating the infiltration of MDSCs in HCC tumor sites via elaboration of IL-17A in γδ T cells." (PMID 33718121, 2020). "In conclusion, we demonstrate in this study that high level of CXCL5 in tumor microenvironment promotes GC metastasis by enhancing GC cell migration and invasion through the induction of EMT." (PMID 32632106, 2020). "This has been shown in a lung cancer murine model, where tumor-aggregated platelets have guided the creation of metastatic sites by the production of CXCL-5 and CXCL-7 cytokines that attract granulocytes." (PMID 32257952, 2020). "In this research, we also found that the expression of CXCL5 in HNSCC tissues were significantly increased when compared with non-tumor tissue." (PMID 33489879, 2020). "Roles of CXCL5 are different in tumor progression due to types of responsive cells in different tumors." (PMID 32201508, 2020). "Recently, studies have demonstrated that CXCL5 expression is correlated with tumor-derived angiogenesis, tumor growth, and metastasis and is also highly associated with inflammatory infiltrates." (PMID 33323542, 2020). "In tumors, IL-4, IL-13, IL-10, TGF-β, and CXCL5 increase tumor cell growth and metastasis through efferocytosis-induced cell clearance and macrophage polarization in the TME." (PMID 32346605, 2020). "In murine tumor models, IL-17 promotes MDSCs tumor infiltration, in a CXCL5/CXCR2-dependent manner, and enhances the immunosuppressive activity of MDSCs." (PMID 32849585, 2020).